MMP9 (matrix metallopeptidase 9)
Diseases named in the same sentence as MMP9 in open-access papers (continued):
Sharing a sentence is not in itself a finding about the gene and the disease.
tumor (continued). "In addition, we demonstrated that CD44 blocking antibody could block MMP-2 and MMP-9 secretion as well as tumor invasion in MCF-7/CD44st cells." (PMID 21749678, 2011). "Matrix Metalloproteinase-9 (MMP-9) is one of them which has the preferential ability to degrade denatured collagens (gelatin) and collagen type IV, the 2 main components of basement membranes and therefore plays a critical role in tumour progression and metastaisis." (PMID 21535879, 2011). "Indeed, it has been shown in tumours that MMP-9 is mostly expressed by these cells." (PMID 20959825, 2010). "MMP9, a member of the matrix metalloproteinases (MMPs), plays a critical role in breakdown of extracellular matrix in normal physiological processes, such as embryonic development, reproduction, and tissue remodeling, as well as in disease processes, such as tumor metastasis." (PMID 20534121, 2010). "Matrix metalloproteinase- 9 (MMP9) can initiate the degradation of certain components of the extracellular matrix and the basal membrane (collagens IV and V, elastin, entactin, casein, and galectin), which promotes the epithelial-mesenchymal transition of tumor cells and stimulates metastasis." (PMID 22649602, 2009). "Therefore, MMP-9 detection in sera could provide significant information of the tumor biological features." (PMID 19889214, 2009). "Moreover, MMP-9 generates growth-proliferating signals and regulates tumor cells proliferation." (PMID 18983651, 2008). "In addition, group 2 showed a significantly higher percentage of tumours positive for TIMP-1, MMP-9 and -11 in the tumour cells; as well as a significantly higher percentage of tumours positive for TIMP-2, TIMP-3, MMP-9, -11, -13 and -14, in fibroblastic cells." (PMID 17848954, 2007). "However, tumours with low levels of MMP9 were found to be less differentiated." (PMID 16001974, 2005). "Thus MMP-9 expression at the invasive front in the resected tumour may indicate the necessity for additional treatment after operation." (PMID 14647147, 2003). "Thus, MMP-9 expression examined by a pre-treatment biopsy of the tumour surface may be a good marker for lymphatic permeation, nodal metastasis and depth of invasion." (PMID 14647147, 2003). "Interestingly, CD44 may act as a tumor cell surface anchor for MMP-9, a matrix metalloproteinase, which may contribute to collagen degradation and contribute to tumor invasiveness." (PMID 19570245, 2002). "Besides MFcells, the MMP-2 and/or MMP-9 mRNAs were expressed by some stromal cell populations(microvascular endothelial cells, fibroblasts, macrophages), suggesting that these cells cooperatein the process of tumor invasion." (PMID 11097203, 2000). "Among the most significantly downregulated proteins were matrix metalloproteinases (MMP‐1, MMP‐9) and uPAR, all of which are central to ECM degradation, tumor cell migration, and vascular invasion." (PMID 41474368, 2026). "Mouse experiments demonstrated that octacosanol significantly reduced tumor p-AKT, MMP2, and MMP9 levels, indicating its in vivo anti-metastatic effect." (PMID 42193927, 2026). "During the invasion phase of the primary tumor, TAMs secrete matrix metalloproteinases (MMPs) (e.g., MMP-2, MMP-9, and MMP-13) to degrade the basement membrane and thus establish a pathway for cancer cell invasion." (PMID 41362730, 2026). "TAMs also promote tumor invasion and metastasis by secreting matrix metalloproteinases (MMP‐2, MMP‐7, MMP‐9, and MMP‐12), cathepsins, and urokinase‐type plasminogen activator, which degrade the extracellular matrix." (PMID 41426206, 2026). "MMP‐2 and MMP‐9 are gelatinases involved in collagen degradation, tumour invasion and angiogenesis, while MMP‐14 activates other MMPs and promotes tumour cell migration." (PMID 41546170, 2026). "N2 neutrophils promote tumor progression by suppressing T cell activity, facilitating angiogenesis via VEGF signaling, and promoting metastasis through MMP9 and NETosis." (PMID 41601690, 2026).
tumor (continued). "Biodistribution and proteomic analyses confirmed efficient BBB penetration, tumor-selective accumulation, and suppression of VEGFA/C, MMP-9, PDGFB, and SERPINE1." (PMID 41993637, 2026). "Although neutrophils contribute only partially to tumour angiogenesis, they exert a unique role in modulating the pro‐angiogenic microenvironment through the secretion of factors like VEGF and MMP‐9, and via NET formation." (PMID 41491612, 2026). "In SW780 tumours and cells, EGCG suppressed the expression of MMP9 and NF-κB at the protein and mRNA levels." (PMID 40427522, 2025). "Neutrophil elastase (NE) and matrix metalloproteinase-9 (MMP-9), both proteolytic enzymes, have been shown to degrade extracellular matrix components, facilitating tumour invasion and metastasis." (PMID 40993312, 2025). "Matrix metalloproteinase 9 (MMP9) exhibited the strongest interaction, consistent with its established role in tumor invasion and metastasis." (PMID 40873584, 2025). "Pathway analysis of 3D tumour spheroids revealed miR-7, alone and in combination with lenvatinib, significantly reduced CAV1, IL8 and MMP-9 mRNA expression." (PMID 40715090, 2025). "Gelatinase (MMP-9) further weakens the ECM, facilitating immune cell infiltration and enhancing the delivery of cytotoxic molecules to tumor sites." (PMID 40227814, 2025). "Matrix metalloproteinases (MMPs) are a family of zinc-dependent proteases that are considered to be crucial for the invasion, tumor angiogenesis and metastasis of BC, with MMP-2 and MMP-9 being correlated with worse patient prognosis." (PMID 41374952, 2025). "HNS induced cell apoptosis and regulated the expression of MMP-9 and TGF-β1, thereby reducing lung metastasis in 4 T1 tumor-bearing mice and altering the tumor microenvironment." (PMID 41220717, 2025). "TGF-β also promotes the expression of MMP-2, MMP-9, and MMP-14, facilitating ECM remodeling and tumor invasion." (PMID 40386422, 2025). "When activated, this domain stimulated the production of matrix metalloproteinase-9 (MMP9), thus attenuating the deposition of tumor collagen and facilitating T cell infiltration." (PMID 40089746, 2025). "We further investigated the expression of key metastatic and invasive markers, matrix metalloproteinase 9 (MMP9) and alpha-smooth muscle actin (SMA) in harvested tumors to assess the impact of food insecurity on tumor aggressiveness." (PMID 40887471, 2025). "Among the MMPs, MMP9 is particularly well‐studied in cancer due to its significant role in ECM remodeling and tumor invasion." (PMID 40739706, 2025). "Magnetic heating with methotrexate-coupled magnetic nanoparticles reduced angiogenic signals (MMP-9, VEGF-R1) in bladder tumors, decreasing tumor size, promoting tumor destruction, and preventing recurrence." (PMID 40284474, 2025). "M2-TAMs release various proteolytic enzymes, including MMP2 and MMP9, which facilitate ECM breakdown and tumor progression." (PMID 40670983, 2025). "While MMP-9, TNC, and POSTN support tumor progression through ECM remodeling, CD163 is involved in tumoral immune suppression." (PMID 41450913, 2025). "MMP2 and MMP9 are members of the MMP family and play a significant role in ECM degradation, thus promoting the migration of tumor cells and their ability to metastasize." (PMID 40566630, 2025). "For instance, the upregulation of miR-378 has been shown to promote brain metastasis via MMP-2, MMP-9, and VEGF regulation, which complements our observation of elevated pS6 and suggests a pro-metastatic tumor microenvironment." (PMID 40805225, 2025). "The expression levels of pro-inflammatory and tumor-related genes, including VEGF, MMP9, TGF-β, TNF-α, COX-2, PGE2, and IL-6, were significantly downregulated in a dose-dependent manner following treatment with ATD-PLGA NPs compared to the untreated group." (PMID 40808199, 2025).
tumor (continued). "TANs exert pro-tumorigenic effects primarily through the secretion of matrix metalloproteinase 9 (MMP9) to degrade extracellular matrix components and upregulation of VEGF, thereby enhancing tumor invasiveness and facilitating metastatic dissemination." (PMID 40563359, 2025). "Tumor-enriched proteases (such as matrix metalloproteinase-2 [MMP2], MMP9, and urokinase plasminogen activator [uPA]3) can cleave the linker and release hemagglutinin (HA)-tagged IL-15 within the TME." (PMID 40532661, 2025). "Resveratrol limits tumor cell invasion by inhibiting the proteolytic enzymes MMP-2 and MMP-9, which degrade the extracellular matrix and facilitate cancer cell migration." (PMID 40572668, 2025). "In vertebrates, tumor cells can upregulate MMP2 and MMP9 for ECM breakdown of the surrounding tissue in order to facilitate tumor progression and metastasis." (PMID 39977429, 2025). "Among them, VEGF provides supporting conditions for the migration and invasion of cancer cells by promoting tumor angiogenesis, and MMP2/MMP9 by degrading the extracellular matrix." (PMID 40786506, 2025). "VEGF (vascular endothelial growth factor) stimulates angiogenesis by interacting with MMP-9 and MMP-14, promoting tumor metastasis." (PMID 39975023, 2025). "NE and matrix metalloproteinase 9 (MMP-9) cut laminin, which induces cascades that result in tumor cell proliferation." (PMID 41343562, 2025). "N2 neutrophils facilitate tumor angiogenesis by releasing factors such as vascular endothelial growth factor (VEGF) and matrix metalloproteinase-9 (MMP-9), and fibroblast growth factor-2 (FGF-2), ultimately promoting tumor proliferation and metastasis." (PMID 41200171, 2025). "M2‐type TAMs, Tregs, and MDSCs promote tumor growth and immune evasion by secreting factors like IL‐10, TGF‐β, VEGF, and MMP9." (PMID 40916616, 2025). "In order to reduce tumor aggressiveness and enhance outcomes for patients with TNBC, this regulatory axis emphasizes the therapeutic potential of targeting the STAT3/MMP-9 pathway." (PMID 40943427, 2025). "Initially, it was believed that TANs primarily functioned as tumor promoters in CRC, contributing to tumor invasion and angiogenesis through the production of MMP9, VEGF, and hepatocyte growth factor (HGF)." (PMID 40255905, 2025). "The research investigates the functional roles of MMP9 and GRP78 in cancer development, their impact on tumour survival through protein upregulation, and the therapeutic efficacy of bioactive compounds derived from the C. caesia rhizome." (PMID 40679956, 2025). "Here we identified that MMP9, MMP13, VCAM1, and PTX3 overexpression not only promotes ECM remodelling and angiogenesis but also facilitates tumour infiltration, thereby reconfiguring the TME to favour migration and metastasis." (PMID 41007296, 2025). "It induced immunogenic cell death (ICD) characterized by calreticulin exposure and ATP release, while modulating the tumor microenvironment by downregulating MMP-3, MMP-9, VEGF, and vimentin, and restoring epithelial markers." (PMID 41304785, 2025). "Its role varies with the stroma-rich tumor microenvironment, involving the activation of FAK, MAPK, and MMP-9." (PMID 40789825, 2025). "Conversely, N2 TANs promote oncogenesis by releasing matrix metalloproteinase 9 (MMP9), which aids angiogenesis and tumor cell spread, while inhibiting natural killer (NK) cell function." (PMID 40387965, 2025). "We have also examined the expression of several tumor aggressiveness markers (MMP‐9, CD44, CD34, PTTG, FGFR4, Ki‐67, E‐Cadherin, and N‐Cadherin) in AF, AD, and PF tumor cells of male rat pituitaries." (PMID 41017273, 2025). "MMPs like MMP1 and MMP9 are involved in cancer development by degrading ECM components, promoting tumor invasion, and metastasis." (PMID 40370880, 2025). "Neutrophils can also influence tumor growth by supporting lympangiogenesis, by increasing VEGF-A bioavailability via the secretion of MMP-9 and heparanase, and by secreting VEGF-D." (PMID 40050933, 2025).
tumor (continued). "MMP9 induces ECM and basement membrane degradation, facilitating microinvasion, proliferation and migration of tumour cells to promote EMT27,49." (PMID 39865173, 2025). "Galectin-1 is involved in tumor invasion, metastasis, and EMT as it controls the expression of MMP-2, MMP-9, and TIMP." (PMID 39996781, 2025). "To further investigate the clinical relevance of aberrantly glycosylated MMP9, we employed double immunofluorescence assays, combining the detection of MMP9 and GNL lectin staining to assess their co-localization within tumor tissues." (PMID 41041068, 2025). "Although more than 10 miRNAs can suppress tumor migration and invasion by regulating MMP-2 and MMP-9, only miR-29b directly targets MMP-2, and only miR-491-5p directly targets MMP-9." (PMID 41356146, 2025). "For example, in zebrafish xenograft models of oral squamous cell carcinoma, shRNA-mediated silencing of MMP9 led to reduced ECM degradation, tumor invasion, and metastatic spread." (PMID 39940643, 2025). "Cardamonin reduced pro-tumor activity of TAMs, decreased M2 markers (CD163, CD206), and suppressed IL-6, VEGFα, MMP2, MMP9 secretion." (PMID 40330466, 2025). "Neutrophils release Mmp9, which degrades collagen and thereby remodels the ECM to promote tumor cell invasion and metastasis." (PMID 39425000, 2025). "The findings highlight curcumin and bis-demethoxycurcumin as promising phytochemical candidates for cancer therapy, capable of modulating MMP9 and GRP78 to suppress tumor progression." (PMID 40679956, 2025). "Elevated MMP9 levels promote ECM breakdown, enabling tumor cells to penetrate adjacent tissues and form distant metastatic lesions." (PMID 41179295, 2025). "M2-like TAMs facilitate proteolytic clearance of interstitial collagen through upregulated MMP expression, including pro-angiogenic TIMP-1-free MMP-9, which, along with neutrophils, increases ECM degradation and tumor invasion." (PMID 41281748, 2025). "MMP9 facilitates ECM degradation, enhancing tumor cell migration, whereas fibronectin supports metastatic cell adhesion, and S100A8/S100A9 contribute to myeloid cell recruitment, generating a pro-inflammatory environment niche." (PMID 40649918, 2025). "The TIMP-1/2/MMP-9 axis correlates with angiogenesis and invasion, and MMP-9 inhibits natural killer (NK) cell function, thereby regulating tumor metastasis." (PMID 40284474, 2025). "The results demonstrated that MCMD NPs enhance drug accumulation in tumors and release DOX after the enzymatic degradation of matrix metalloproteinase-9 (MMP9) in the TME, thereby enhancing the direct cytotoxic effect of DOX on tumor cells." (PMID 39861716, 2025). "N1 TANs directly kill tumor cells via cytotoxic agents (H2O2, TNF-α), whereas N2 TANs promote tumor progression by secreting ROS, VEGF, and MMP-9 to induce angiogenesis, matrix degradation, and immunosuppression." (PMID 41459159, 2025). "Among these, MMP9 facilitates ECM degradation, enhancing vascular permeability and promoting tumor cell extravasation, while S100A8 fosters a pro-inflammatory microenvironment that sustains neutrophil survival and function." (PMID 40649918, 2025). "The expressionof BCL2, which is decreased in tumor hepatocytes, canbe suppressed by four proteins (CDK1, VDAC1, MMP9,CYC), the expression of which is increased in malignant hepatocytes compared with hepatocytes from healthy livertissue." (PMID 41541554, 2025). "Anti-metastatic effects emerge through MMP2 and MMP9 downregulation coupled with EMT reversal, as validated by immunohistochemical analyses in xenograft tumor tissues." (PMID 41511301, 2025). "This was further demonstrated therapeutically, with a micellar nano system containing calcitriol reducing BC tumor growth and metastasis via the down-regulation of MMP-2 and MMP-9, while at the same time up-regulating the focal adhesion protein paxillin." (PMID 41374952, 2025).
tumor (continued). "While there is compelling evidence of localized tumor‐promoting effects, such as increased migration and invasion, we also observed alterations in potential downstream factors of ADAMTS13, such as MMP9, that have multifaceted functions in human cancers." (PMID 41211185, 2025). "TGFB1 is essential for invasive growth and proliferation in GC tumor cells, such as GCTM-1 GC cell line, in which TGFB1 induces enhanced expression of matrix metalloproteinase 9 (MMP9) and PLAU in tumor cells." (PMID 40075643, 2025). "Therefore, further in vivo investigations are important to determine whether these compounds can reach sufficient concentrations at tumor sites to exert meaningful biological effects, particularly in modulating MMP-2 and MMP-9 expression and thereby inhibiting tumor progression and metastasis." (PMID 40563423, 2025). "Previous studies have established that MMP9 suppresses CD8+ T cell infiltration and activation and promotes an immunosuppressive environment, underscoring its critical function in tumor immunosuppression." (PMID 41306770, 2025). "IL-6 also promoted angiogenesis, tumor invasion, and metastasis through the regulation of hypoxia-inducible factor 1α (HIF-1α), matrix metalloproteinases (MMP2, MMP7, MMP9), and vascular endothelial growth factor (VEGF)." (PMID 40160826, 2025). "Through the production of matrix metalloproteinases (MMPs), such as MMP2 and MMP9, CAFs break down ECM barriers, facilitating tumor cell migration and invasion." (PMID 39940643, 2025). "VEGF activates MMP-9: Through pathways such as hypoxia-inducible factor (HIF-1α), VEGF increases the expression of MMP-9, particularly in the tumor microenvironment." (PMID 41255610, 2025). "Western blot results subsequently displayed that HIPK4 knockdown significantly reduced HIPK4, TAp63-pS395, Ki67, MMP2, and MMP9 levels, but elevated EFEMP1 levels in tumor tissues." (PMID 40316017, 2025). "Previous studies have demonstrated that neutrophils release neutrophil elastase (NE), cathepsin G (CG) and matrix metalloproteinases 9 (MMP9) to remodel the ECM, ultimately leading to tumor growth and metastasis." (PMID 40963631, 2025). "(K) Western blotting of macrophage pro-tumor indicators (VEGF, MMP9, TGF-β, and HIF-1α) in S100a4-OE MH-S." (PMID 40658605, 2025). "Canonical markers were used to annotate different cell types: malignant cells (COL1A1, IBSP), myeloid cells (CD74, CD14), osteoclasts (CTSK, MMP9), pericytes (RGS5, ACTA2), endothelial cells (PECAM1, VWF), and tumor-infiltrating lymphocytes (CD3D, NKG7)." (PMID 40730548, 2025). "Single-cell RNA sequencing (scRNA-seq, GSE159115) was used to assess tumour heterogeneity, while in vitro experiments in RCC cell lines validated MMP9’s impact on anoikis resistance, migration and invasion." (PMID 40830065, 2025). "This pathway enhances tumor invasiveness by facilitating epithelial–mesenchymal transition (EMT) and upregulating MMPs such as MMP-2 and MMP-9." (PMID 41153831, 2025). "A potential regulatory link between MMP9 and SLC12A5-AS1 highlights the relevance of non-coding RNAs in modulating MMP-mediated tumor progression." (PMID 40604111, 2025). "BMDCs play a central role in cancer metastasis by orchestrating the immunosuppressive PMN through ECM remodeling, such as the production of MMP9 and S100A8/A9, which facilitate tumor cell extravasation and colonization." (PMID 40470380, 2025). "These were the two most upregulated genes in G3 tumor compartments adjacent to α‐SMA+ stromal cells; however, these results should be interpreted carefully as only the MMP9 had an FDR value of < 0.05." (PMID 39245631, 2025). "Matrix metalloproteinases (MMPs), particularly MMP-2 and MMP-9, are Zn2+-dependent endopeptidases that degrade ECM structural components, facilitating tumor dissemination and invasion." (PMID 40940940, 2025).